CD4 (CD4 molecule)
Diseases named in the same sentence as CD4 in open-access papers (continued):
Sharing a sentence is not in itself a finding about the gene and the disease.
Cirrhosis (continued). "The following baseline factors were associated with death: male gender (Hazard ratio [HR] 1.96, 95% CI 1.19–3.24), CD4 cell count <100 cells/mm3 (HR 2.06, 95% CI 1.48–2.87), history of an AIDS-defining illness (HR 2.01, 95% CI 1.36–2.96), cirrhosis (HR 1.95, 95% CI 1.36–2.81)." (PMID 21490781, 2011). "They show that unsuccessful HCV treatment was more common among people with a CD4+ cell count less than 350, among both people with and without cirrhosis, and suggest that a low CD4+ cell could likely play a role in unsuccessful HCV treatment." (PMID 39656170, 2025). "Moreover, we observed minor changes in clustering of CD8+ T cells and CD4+ T cells between patients without liver cirrhosis compared with compensated cirrhosis and decompensated cirrhosis." (PMID 41028194, 2025). "The CD4+ T cell population was contracted in cirrhosis, regardless of mice age." (PMID 39656486, 2024). "Additionally, the proportion of CD4 T cell-TNFAIP3, CD8 T cell-TNF (effector CD8 T cells), and CD8 T cell-CD53 increased, while the proportion of Treg cells decreased from HBV infection to cirrhosis." (PMID 38116005, 2023). "Similarly, BE from NAFLD-HCC subjects attenuated the expansion of total CD4+ T cells (CD3+CD4+) compared to NAFLD-cirrhosis and non-NAFLD control BE (P < 0.0001)." (PMID 33420074, 2021). "As for the analysis on cirrhosis, we have not obtained an overlap cell type in the two methods, with CD4 + T cell significant in RolyPoly analysis using the GWAS data on East Asian population, while NKT and hepatocyte are significant in RolyPoly analysis on European population." (PMID 33763117, 2021). "However, HBV infection and cirrhosis were more common among cases compared to controls, regardless of CD4 nadir status." (PMID 30315476, 2018). "Moreover, CD4+ T cells from patients with compensated liver cirrhosis displayed a differentiation trajectory towards an effector-memory phenotype, whereas frequencies of effector-memory cells in decompensated cirrhosis were comparable to healthy and/or non-cirrhosis patients." (PMID 41028194, 2025). "Our results suggest that after treatment with 90Y, there is a shift from TCM to TEM cells following 90Y for both CD4+ and CD8+ T cells independent of cirrhosis etiology." (PMID 39069671, 2024). "In contrast, CD4+ and CD8+ T cells of patients with acutely decompensated cirrhosis or with ACLF did not respond to stimulation with PMA/ionomycin with induction of IFN-γ and TNF-α." (PMID 33574809, 2020). "The SVR12 rates were high in OBV/PTV/r ± DSV ± RBV for HIV/HCV GT1 coinfected patients regardless of the duration of treatment, regimens, HCV genotypes, history of treatment, and the presence or absence of cirrhosis, baseline HCV RNA, CD4 cell counts, Platelet counts, and IL 28B genotype." (PMID 30654809, 2019).
breast tumor (124 papers, 2011 to 2026). "Abundant naïve CD4 cells were shown to be associated with poor patient prognosis and upregulated Tregs in breast tumors." (PMID 40574005, 2025). "BRCA-mutated breast tumors are also characterized by the presence of TILs such as CD4+, CD8+, and FOXP3+ T lymphocytes." (PMID 38134458, 2023). "Supporting this observation, it was shown that DNA repair-deficient breast tumors were associated with CD4+ and CD8+ lymphocyte infiltration and that cells from these DNA repair-deficient breast tumors expressed the chemokines CXCL10 and CCL5 more strongly." (PMID 37420037, 2023). "The decomposition results from SpaCET showed that the breast tumor comprises mainly malignant cells, cancer-associated fibroblasts (CAFs), endothelial cells, macrophages, and T CD4 cells." (PMID 36732531, 2023). "Rag1KO mice that received WT CD4+ T cells were protected from Brca1-deficient breast tumor growth accompanied by the development of low-grade tumors compared with the Rag1KO + TslprKO CD4+ T cell control group (P = 0.0001)." (PMID 35657353, 2022). "Next, we report how MicroCellClust highlights a small subpopulation with a specific phenotype inside CD4 T cells from breast tumor samples, as well as a small subpopulation linked to cell cycle activity among activated Tregs." (PMID 33830183, 2021). "Comparison of FH-deficient and high-FH breast tumors revealed a significant increase in activated mast cells, which are implicated in tumor proliferation and angiogenesis, with an additional increase detected in resting memory CD4+ T cells." (PMID 41008787, 2025). "They found that DDRD breast tumors were associated with infiltration of CD4+ and CD8+ lymphocytes." (PMID 34884892, 2021). "Moreover, a rich CD4+ Th1 signature in breast tumors has been associated with a good prognosis." (PMID 32601304, 2020). "We demonstrate that targeting CD73 in qM breast tumors sensitizes them to anti-CTLA4 ICB therapy in a CD4+ T cell-dependent manner." (PMID 42118667, 2026). "In the tumor microenvironment, CD4+ T cells have been reported to accumulate around breast tumors in vivo." (PMID 41225146, 2025). "Compared with the other groups, the G‐STEPT showed increased proportions and numbers of CD8+ T cells, with little effect on CD4+ T cells in the breast tumor‐bearing model mice at 14 days." (PMID 41476656, 2025). "The DEG analysis showed that the EIF5A expression in CD4+ T cell was significantly downregulated in breast tumor cells versus normal cells (logFC = −0.21, p = 1.4 × 10−4), which is the same direction of effect as our MR findings." (PMID 41216857, 2025). "By contrast, TSLP induction stimulates the specific expansion and antitumor functionality of CD4+ Th2 cells in spontaneous and cell line–derived breast tumors." (PMID 39782693, 2025). "To this end, we analyzed a previously published data set containing single-cell transcriptomes of CD4+ T cells isolated from primary human breast tumors and the PB from the corresponding patients." (PMID 39211051, 2024). "Here we monitored intratumoral and splenic CD8 + or CD4 + T cells longitudinally in response to ICB treatment in immunologically “cold” breast tumors using [89Zr]Zr-DFO-CD8 or [89Zr]Zr-DFO-CD4 PET imaging." (PMID 38918836, 2024). "Tumor-infiltrating naive CD4+ T cells are recruited to breast tumors by CCL18 and converted to functional immunosuppressive Tregs." (PMID 36418470, 2023). "Similar to the breast tumor samples, we observed increased frequencies of CD4 + Th1 cells after TOP2A vaccination." (PMID 37880313, 2023). "Since, the expressions of the gene signatures do not necessarily correlate with the actual number of cells, in our fifth approach, we directly evaluated the percentage of CD4+CD25+FOXP3+ Tregs from breast tumor patient-derived blood samples." (PMID 38038865, 2023).
breast tumor (continued). "In a comprehensive study on infiltrating CD4+ T-cells in untreated invasive primary breast tumors, the Gallo group reported, for the first time, the presence of Tfh cells among infiltrating lymphocytes in BC." (PMID 37835465, 2023). "We analyzed CD4 + T cells from the breast tumors and identified three types of CD4 + T cell subsets including CD4 Th1, CD4 Th17 and Treg cells." (PMID 37880313, 2023). "High levels of CD4+T-regulatory cells in breast tumors are associated with reduced OS, whereas high levels of CD8+T cells combined with low levels of CD4+T-regulatory cells correlate with increased OS." (PMID 34875483, 2022). "Compared to the control, SI-2 treatment significantly reduced the numbers of both CD4 + /Foxp3 + and CD4-/Foxp3 + cells in E0771 breast tumors." (PMID 36316775, 2022). "Our dual immunofluorescence staining revealed that SI-2 treatment also reduced the numbers of CD4-/Foxp3 + tumor cells in E0771 breast tumors." (PMID 36316775, 2022). "This analysis suggested that the ER+ breast tumors with high miR-18a levels have a higher CD4/CD8 ratio, higher proportion of T-regulatory cells, and exhausted CD8 + T cells." (PMID 35626709, 2022). "Instead of cellular cytotoxicity, the tumor-suppressive phenotype is mediated by cellular senescence, in which effector CD4+ T cells can directly block advanced breast tumor development." (PMID 36467403, 2022). "Treatment with 2.5 mg/kg SI-2 elevated the levels of CD4 + and NK cells in 4T1 breast tumors compared to the vehicle controls." (PMID 36316775, 2022). "NIR-PMC-treated tumours showed lower A2AR expression but enhanced CD4 expression, suggesting the occurrence of enhanced anti-cancer immune response in breast tumours." (PMID 35918337, 2022). "In contrast, TnfKO and IfngKO CD4+ T cells blocked PyMtOvatg TslprKO breast tumor growth and induced the differentiation of the high-grade donor tumors into low-grade fibrocystic structures in Tslptg TslprKO mice." (PMID 35657353, 2022). "Breast tumors of Tslp-PyMttg Rag1KO mice that received CD4+ T cells had significantly lower histological grades and lacked metastatic potential compared with control groups (P = 0.0149)." (PMID 35657353, 2022). "PyMttg TslprKO primary breast tumor cells generated significantly smaller tumors in Tslptg TslprKO mice that received WT CD4+ T cells compared with TslprKO CD4+ T cells (P = 0.0087)." (PMID 35657353, 2022). "The IHC results validated a part of 39 clinical breast tumor samples had distinct CD4+, CD8+, and regulatory T cell infiltration." (PMID 34804948, 2021). "Here, we show that patients with untreated breast tumors exhibit an accumulation of not only CD8+ but also CD4+ senescent T cells in peripheral blood." (PMID 34386013, 2021). "The majority of the CD4+ T cells in all breast tumors are TEM (CD45RA−CCR7−; 88%), followed by a small group of TEMRA (CD45RA+CCR7−; 8%), TCM (CD45RA−CCR7+;4%), and TNAIVE (CD45RA+CCR7+; 1%)." (PMID 33467084, 2021). "In this study, we demonstrated that tumor necrosis factor receptor 2 (TNFR2) is highly expressed in both breast tumor tissue and tumor-infiltrating immunosuppressive CD4+Foxp3+ regulatory T cells (Tregs)." (PMID 34900985, 2021). "In a reported IL-12→27 sequence, the growth of immunogenic colon and breast tumors was suppressed through a CD4 and CD8 T cell and IFNγ-based anti-tumor response." (PMID 34209203, 2021). "Blocking macrophage infiltration or inducing a Th1 phenotype in CD4+ T cells significantly attenuates breast tumor growth." (PMID 34283809, 2021). "CD4+ T cells in highly infiltrated breast tumors of all subtypes are also phenotypically skewed towards the T follicular helper cells (TFH) phenotype, characterized by CD200, ICOS, CXCL13, and a high level of PD-1." (PMID 33467084, 2021). "Together, these data indicate that treatment with ivermectin induced hallmarks of ICD within 4T1 breast tumors and recruited large numbers of CD4+ and CD8+ T cells into these tumors." (PMID 33654071, 2021).
breast tumor (continued). "CT inhibited breast tumor MCF-7 growth by triggering proliferation and increasing perforin secretion of CD4+ T cells which is associated with enhancement of the p-JAK 2 and p-STAT 4 expressions." (PMID 32265690, 2020). "The diversity of the CD4+CD25+ TCR β CDR3 repertoires in breast tumor tissue was similar to that of lung metastatic tissues and less pronounced than that of spleen tissues." (PMID 33029539, 2020). "A high proportion of CD4+CD25+ T cells samples in the breast tumor tissues, lung metastatic tissues, and spleens of tumor-bearing mice were separated." (PMID 33029539, 2020). "The results also showed that breast tumor tissues and metastatic tumor tissues had greater frequencies of cloning CD4+CD25+ T cells, which made it possible to promote tumor growth and metastasis." (PMID 33029539, 2020). "The positive staining numbers of CD8+ and CD4+ T cells infiltrated in breast tumors were measured by immunohistochemistry to evaluate the antitumor immunity of SSa." (PMID 31214035, 2019). "In line with previous studies, we observed significant accumulation of CD4+FoxP3+ Tregs in breast tumors (13.4 ± 2.3%), compared with NT (2.9 ± 1.3%)." (PMID 28388539, 2017). "We used breast tumor tissues from each patient to make tissue microarrays that were then stained for leukocyte and myeloid markers including CD4, CD8, CD20, CD25, CD68, and CD163 using immunohistochemical techniques." (PMID 28794686, 2017). "In our previous studies, we observed that breast tumor cells produce an abundant amount of TGFβ which can induce FOXP3 in the CD4+ naïve cell to differentiate them into Treg cells." (PMID 28487507, 2017). "Here, we demonstrate that in MMTV-PyMT, a highly malignant spontaneous breast tumor model, IL-25 (also called IL-17E) was expressed by tumor-infiltrating CD4+ T cells and macrophages." (PMID 27909985, 2017). "The numbers of CD4/CD8/Foxp3-positive cells were also significantly greater in the primary breast tumors than in the brain metastases (paired t-test, P < 0.05 [all categories])." (PMID 29262592, 2017). "Our data suggest that naive CD4+ T cells are recruited from the blood to breast tumors, where they can differentiate into immunosuppressive Tregs." (PMID 28290464, 2017). "Taken together, our results indicate that both CD4+ and CD8+ memory T cells specific for multiple breast tumor-associated antigens are induced during pregnancy and persist for decades." (PMID 29285226, 2017). "Based on expression data, CCL18 is an attractive candidate chemokine for recruiting naive CD4+ T cells to breast tumors." (PMID 28290464, 2017). "In a separate study, NHS-muIL12 treatment of BALB/c mice bearing EMT6 breast tumors also increases PD-1 on CD4+ and CD8+ T cells and PD-L1 expression levels on tumor-associated macrophages, neutrophils and dendritic cells." (PMID 28423552, 2017). "TAMs usually acquire a skewed M2-like phenotype oriented to tumor promotion and it has been reported that Th2 CD4+ T cells promote breast tumor progression and metastasis by educating TAMs to produce pro-angiogenic and pro-metastatic factors." (PMID 28533483, 2017). "In line with this evidence, treatment with anti-IL-25 blocking antibody significantly reduced IL-4-producing CD4+ Th2 cells in the MMTV-PyMT breast tumor model." (PMID 27909985, 2017). "In this study, we found a significant accumulation of CD3+ T cells within breast tumor tissues, and this increase was observed in both CD4+ and CD8+ T cell subsets." (PMID 28388539, 2017). "The expanded CD4+ T cells within the breast tumor tissue also expressed high levels of CD25, PD-1 and CD39 compared with their levels in normal breast tissue, indicating their activated but “exhaustive” state." (PMID 28388539, 2017). "The numbers of CD4/CD8/Foxp3-positive cells were significantly higher in primary breast tumors than in brain metastases (paired t-test, P < 0.05 for all antibodies)." (PMID 29262592, 2017).
breast tumor (continued). "Here we show that the TAM-produced chemokine CCL18 recruits circulating naive CD4+ T cells to breast tumors by binding their PITPNM3 receptor." (PMID 28290464, 2017). "To confirm the role of PITPNM3 in naive CD4+ T cell recruitment to breast tumors and elucidate the role of naive CD4+ T cell infiltration in Treg generation and cancer progression in vivo, we employed a humanized mouse tumor model." (PMID 28290464, 2017). "In the present study, we evaluated the percentages of CD4+ T cells and its subsets in the PBMCs of breast tumor patients." (PMID 27762298, 2016). "Given that significant increase of CD4/CD8 ratio was observed in the late stage of breast tumor models, we therefore determined the alterations of Foxp3+CD4/CD8 T cell ratios in the different tumor developmental stages." (PMID 25968569, 2015). "In an aggressive breast tumor-mouse model IL-4-producing CD4+ T lymphocytes indirectly promoted invasion and subsequent metastasis of mammary adenocarcinomas by regulating the phenotype and effector function of tumor-associated macrophages." (PMID 22176642, 2011). "Based on the MMTV-PyMT breast tumor mouse model, in which these authors also found a relation between macrophages, CD4 T cells and poor outcome, the CD4 T cells are likely to be Th2 cells." (PMID 22176642, 2011). "In this study, we examined the changes of ILC1, ILC2, and ILC3 frequency in innate immunity, CD4+ and CD8+ T cells in adoptive immunity, and the expression of their associated cytokines (IFN-γ, IL-4, IL-10, IL-13, and IL-22) in 4T1 and MC4-L2 breast tumor models." (PMID 39877637, 2025). "The CCL5-CCR3 signaling axis induced Th2 polarization of CD4+ T cells in a breast tumor model." (PMID 39566333, 2025). "Notably, upregulation in these patients was largely restricted to A2AR, 2B4, and CCL17, suggesting the potential involvement of alternative pathways in regulating CD4+ T cell function within siglec-7 high breast tumor microenvironment." (PMID 40547037, 2025). "In addition, a recombinant TWIST1 protein has been used as a vaccine to induce both CD8+ and CD4+ TWIST1-specific T-cell responses in vivo to attack TWIST1-expressing breast tumor cells with certain efficacy." (PMID 38893094, 2024). "To identify whether this signature was maintained during tumor growth, we used the 4T1 murine breast tumor model and, again, evaluated the cytokines produced by CD4+ T lymphocytes, in the same organs, which are target organs of metastasis in the model." (PMID 38690280, 2024). "TOP2A vaccine treatment significantly increased the proportion of CD4 + Th1 and Th17 cells in breast tumors while decreasing the abundance of Treg cells, suggesting that the anti-tumor function of CD4 + T cells was significantly enhanced by TOP2A vaccine treatment." (PMID 37880313, 2023). "We implanted primary breast tumors from PyMtOvatg Csf2rbKO Csf2rb2KO mice into the abdominal mammary fat pad of Tslptg TslprKO recipient mice a day after adoptive WT CD4+ T cell (test) versus TslprKO CD4+ T cell (control) transfer into these animals." (PMID 35657353, 2022). "Both CD4 + /Foxp3 + and CD4-/Foxp3 + cells were detected in control E0771 breast tumors." (PMID 36316775, 2022). "Therefore, SI-2 treatment suppresses E0771 breast tumor progression in immune-intact mice by recruiting CD4+ and CD8+ T cells into tumors." (PMID 36316775, 2022). "Il3KO CD4+ T cells suppressed PyMtOvatg TslprKO breast tumor growth in Tslptg TslprKO mice." (PMID 35657353, 2022). "Less than 15% of breast tumor cell pyroptosis could eliminate the entire 4T1 tumor graft by activating cytotoxic T cells and CD4+ T helper cells." (PMID 35664308, 2022). "Importantly, the persistent tumor suppression was mediated by the reversion of the breast tumors into low-grade fibrocystic structures surrounded by significant CD4+ T cells in the test group compared with high-grade tumors in the controls (P = 0.0119)." (PMID 35657353, 2022).